APOE (apolipoprotein E)
Diseases named in the same sentence as APOE in open-access papers (continued):
Sharing a sentence is not in itself a finding about the gene and the disease.
diabetes (continued). "Chemical inhibition of Glo1 in apoE−/− mice is able to increase endothelial inflammation and atherogenesis in the absence of hyperglycaemia, to a similar extent as in hyperglycaemic mice with diabetes." (PMID 28106778, 2017). "Some clinical studies have not confirmed the association between AD and diabetes, with the exception apolipoprotein E (ApoE) ε4 allele carriers." (PMID 28589443, 2017). "Only the interaction between APOE e4 and diabetes survived FDR correction." (PMID 28324763, 2017). "Furthermore, GLM indicated factors impacting MMSE ranking were the interaction between APOE ε4 allele and frontal WMH volume, independent to vascular risk factors (hypertension, diabetes mellitus and smoking history) and other CSVD." (PMID 28574812, 2017). "In this study, we investigated the reno-protective effect of PIO in apolipoprotein E (apoE)-knockout (-/-) mice with diabetes, with a particular emphasis on the relationship between PIO and alterations in NLRP3 inflammasome activation, as well as the underlying mechanisms." (PMID 28708885, 2017). "Within a cross-sectional analysis, participants of the German Diabetes Study (n = 348) with mean T2D duration of 6 months were investigated for fasting serum lipid levels, ApoA5 and ApoE genotypes; food consumption frequencies were assessed by a food propensity questionnaire." (PMID 27677442, 2016). "Smoking, depression, low education, midlife hypertension, midlife obesity, diabetes, physical inactivity, and nonmodifiable risk factors like age, sex, and genetics like apolipoprotein E genotype (APOE ɛ4) have been associated with increased risk for MD." (PMID 27317923, 2016). "Previous research has shown that people with diabetes are more likely to present with dyslipidemia than those without diabetes, and that the APOE gene is associated with lipid metabolism and heart disease." (PMID 26998902, 2016). "Furthermore, several pathological states including hypertension, carotid atherosclerosis, Apolipoprotein E (ApoE), and diabetic mellitus, which increase the incidence of cerebral ischemia, are closely linked to the development of AD." (PMID 26632816, 2015). "Diabetes was related to an augment of ~35% in the kidney weight/body weight ratio when compared with ND mice (p < 0.05), whereas quercetin reversed this consequence of diabetes in the apoE−/− mice (p < 0.05)." (PMID 26388784, 2015). "The negative interaction of PP with APOE ε4 allele and marginally significant interaction with diabetes are interesting, but the implications are unclear." (PMID 26441635, 2015). "Also it was shown that interaction of butyrylcholinesterase (BChE K) and apolipoprotein E (ApoE) was associated significantly with CAD and diabetes." (PMID 26587547, 2015). "To limit the impact of vascular risk factors on the observed group difference in WMH volume, we controlled for blood pressure, diabetes and coronary heart disease, as well as antihypertensive and cholesterol-lowering treatment, and we found that the APOE-dependent effect on WMH volume persisted." (PMID 25984242, 2015). "Streptozotocin (STZ)-induced diabetes in apolipoprotein E−/− mice resulted in 2.2 fold increased aortic atherosclerosis and enhanced pro-inflammatory burden, as evidenced by elevated blood monocytes, endothelial activation- and inflammatory markers in aorta, and pro-inflammatory cytokines in plasma." (PMID 23755169, 2014). "To test this hypothesis we used SPECT molecular imaging for quantifying VEGFR prevalence in plaques in apolipoprotein null (ApoE−/−) mice in which complex plaque development is accelerated by induction of diabetes." (PMID 26055940, 2014). "Moreover, it was recently suggested that the effect of diabetes on cognitive function is possibly modified by APOE ε4 carriership in middle-aged and old people." (PMID 24367577, 2013).
diabetes (continued). "We have developed a radiolabeled murine monoclonal antibody targeting RAGE for in vivo imaging of RAGE expression and have shown focal uptake of this probe in atheroma in apolipoprotein E-deficient (apoE−/−) mice both with and without diabetes." (PMID 23663412, 2013). "In addition to APOE genotype, MCI diagnosis, and type 2 diabetes mellitus, there are several other known risk factors for AD including major depression, hypertension, cardiovascular disease, and obesity." (PMID 24961307, 2013). "If the analyses were repeated after exclusion of all APOE ε2 carries, the negative association of diabetes with RFFT score and the interaction between diabetes and age were also found." (PMID 24367577, 2013). "Recently, it was found that the effect of diabetes on cognitive function may be modified by APOE ε4 carriership." (PMID 24367577, 2013). "Consequently, we investigated the effects of ME in an in vivo model of diabetes, the ApoE/GPx1 double knockout (dKO) mouse." (PMID 23874911, 2013). "This study tentatively supports the fact that variability in apoE gene locus is associated with diabetes with and without CAD complication by influencing the plasma lipid levels that are important risk factors for both T2DM and CAD." (PMID 22520940, 2012). "A smaller islet mass and more prominent islet inflammation may explain the vulnerability of B6.apoE-/- mice to diet-induced diabetes." (PMID 22204493, 2011). "ApoE is also an important molecule in the development and progression of diabetes." (PMID 22028770, 2011). "No significant changes were detected in retinas of ApoE or TNFα deficient mice in response to diabetes." (PMID 20856927, 2010). "The effect of diabetes on the expression of various inflammatory (TNFα, IL-6, IL-1β and IFNγ) and apoptosis markers (caspase-1) was also evaluated in intact retinas from wt, ApoE−/−, TNFα−/− and ApoE−/−/TNFα−/− mice." (PMID 20856927, 2010). "Collectively, it seems that diet-induced VCAM-1 expression may be driven by serum cholesterol, whereas diabetes-induced ICAM-1 expression may be driven by triglycerides in ApoE−/− mice, by a mechanism yet to be described." (PMID 20856927, 2010). "The Drug Metabolism–Cytochrome P450 pathway was downregulated in tissue samples from recovered diabetic foot patients compared to those from the disease group, suggesting that the APOE+ subpopulation might influence the onset and progression of diabetes through this metabolic pathway." (PMID 40612951, 2025). "Additionally, a significant association was observed between diabetes and CSF tau levels in APOE E4+ carriers, but not in APOE E4- individuals." (PMID 39596023, 2024). "Additionally, among individuals older than 60 years old, not carrying the APOE ε4 gene, no diabetes or mildly cognitively impaired, the risk of developing AD decreased with each unit increase in the TyG-BMI index." (PMID 38997334, 2024). "Nonetheless, some factors such as sex, APOE genotype or health status, seem to modify the effect of exercise training, as favourable and significant findings regarding Aβ levels were reported in women with obesity, pre-diabetes, or depression and in APOE-ε4 carriers individuals with AD." (PMID 38803456, 2024). "In the present study, we performed a correlation analysis to consider the influence of several covariates (e.g., sex, race, education, ApoE genotype, diabetes, and hypertension) that may affect the relationship between α-T stereoisomer profile and cognitive health." (PMID 39199242, 2024). "In stratified analyses, the magnitude and direction of the association between kidney function and gray matter volume remained similar regardless of diabetes status, hypertension status, and APOE genotype, but the associations became nonsignificant in each stratum." (PMID 37578935, 2024).
diabetes (continued). "Notably, our analysis revealed that, when accounting for additional covariates such as age, gender, education, hypertension, diabetes mellitus, hyperlipidemia, and smoking, the influence of APOE genotype on the microvascular density of SVC was more pronounced compared to cognition." (PMID 37685715, 2023). "The difference with our results regarding glucose metabolism could be explained by the difference in genotypes, as LDL receptor but not apolipoprotein E deficiency increases diet-induced obesity and diabetes in mice." (PMID 36831200, 2023). "After adjustment for classical diabetes risk factors, glucose parameters (FPG, HbA1C), and plasma TG, we ultimately identified 4 apolipoproteins amongst 16 that remain significantly associated with new-onset T2D in individuals with prediabetes: apoE, apoF, apoJ, and apoL1." (PMID 35130909, 2022). "However, neither vascular risk factors (hypertension, diabetes mellitus, and hyperlipidemia) nor the number of ApoE ε4 carriers was significantly different between the groups." (PMID 35821150, 2022). "Phytosterol composition, the characteristics of its food matrix, clinical conditions that affect cholesterol metabolism such as type 2 diabetes mellitus (DM2), and single-nucleotide polymorphisms (SNPs) in NPC1L1 and apolipoprotein E (ApoE) may modify both their bioavailability and their efficacy." (PMID 35406067, 2022). "A recent animal study has also suggested that irisin treatment suppressed endothelial injury and reduced the degree of aortic atherosclerotic plaque in apolipoprotein E-knock out diabetic mice, suggesting irisin could be therapeutic for atherosclerotic vascular diseases in diabetes." (PMID 35557850, 2022). "However, we adjusted for vascular disease risk factors, such as hypertension, smoking, and diabetes, in our models, and a preliminary study did not reveal a positive correlation between ApoE status and HL." (PMID 33627087, 2021). "Adjusting for risk genes (ABCA7, APOE) and other factors (hypertension, cardiovascular risk score, white matter hyperintensities, and diabetes) did not significantly influence connectivity values and race-associated differences persisted in connectivity relationship." (PMID 32099645, 2020). "However, we could eliminate the possible influence of other chronic illnesses, e.g. diabetes or treatment on APOE level and other lipid and apolipoprotein parameters." (PMID 30851738, 2019). "Our data show that overall NO availability at the tissue level is not reduced sixteen weeks after the induction of diabetes in apoE knockout mice, despite the presence of factors that cause endothelial dysfunction, and the presence of the endogenous NOS inhibitor ADMA." (PMID 28103268, 2017). "In addition, patients with T2DM who carry the ApoE-ε4 allele are two-fold more prone to develop AD than those without diabetes." (PMID 28589443, 2017). "For example, in contrast with control mice, FABP4-deficient mice did not develop insulin resistance or diabetes in diet-induced obesity mode and Fabp4 mRNA expression in circulating leucocytes isolated from Apoe−/− (apolipoprotein E-null) mice was correlated with atherosclerotic lesion size." (PMID 26823558, 2016). "Moreover, diabetes was associated with a significant reduction of body weight and a significant increase of total cholesterol as compared to nondiabetic ApoE−/− mice." (PMID 28070143, 2016). "Thus, elderly community dwelling residents of Han ethnicity carrying the APOE ε3/ε3 genotype might have higher plasma glucose levels and a higher occurrence of diabetes." (PMID 26998902, 2016). "This could have resulted in a higher random error, which could be one of the reasons that variation in APOE was associated with diabetes, but not with serum glucose levels in participants without diabetes." (PMID 27540764, 2016). "However, the association of PP with MCI varied significantly by APOE ε4 allele, and non-significantly, by diabetes status." (PMID 26441635, 2015).
diabetes (continued). "As an example, some of the lipid-lowering effects of PPARγ agonists, attributable to defects in fatty acid use or storage are only observed in the context of diabetes, but not in nondiabetic atherosclerotic models in which the dyslipidemia is caused, for example, by defective ApoE." (PMID 25785279, 2015). "We show that overexpression of an enzyme that participates in the pathway of methylglyoxal detoxification, glyoxalase 1, protects streptozotocin‐treated, apolipoprotein E‐deficient mice from diabetic kidney disease but not from diabetes‐induced accelerated aortic atherosclerosis." (PMID 24920125, 2014). "For the clustering of CRFs where stage 2 hypertension, high CRP, obesity, diabetes and smoking were aggregated, we found that the likelihood of mobility limitation increased linearly with increasing number of CRFs, when adjusting for demographics and APOE genotype (model 1)." (PMID 23741513, 2013). "The association of diabetes with RFFT score was not modified by APOE ε4 carriership." (PMID 24367577, 2013). "APOC3 ASO also altered the LDL and TRL/RLP proteome in a manner characteristic of increased lipoprotein particle clearance, with reduced levels of APOCs and APOE, indicating that APOC3 ASO normalized the slowed RLP clearance in diabetes." (PMID 40709279, 2025). "Age, sex, race, education, APOE ε4 genotype, alcohol use, eGFR, BMI, blood pressure, HDL, total cholesterol, hypertension, and diabetes." (PMID 41262081, 2025). "Dyslipidemia is a co-existing problem in patients with diabetes mellitus (DM) and coronary artery disease (CAD), and apolipoprotein E (APOE) plays an important role in lipid metabolism." (PMID 38491412, 2024). "Specifically, genes such as CCL17, CD163, APOE, CYP27A1, and STAB1, some of which are recognized as anti-atherogenic and anti-inflammatory factors in diabetes patients, were identified within this module." (PMID 38658734, 2024). "To model diabetes-induced metabolic alterations of the kidney, we performed repeated injections of streptozotocin (STZ) in apolipoprotein E (ApoE) knock out mice 19,20." (PMID 37069341, 2023). "APOE ε4 carriers showed reduced SVC density (p = 0.023) compared to APOE ε4 non-carriers in all participants when considering age, gender, education, diabetes, hypertension, hyperlipidemia, and smoking as covariates." (PMID 37685715, 2023). "The consistent results were observed in regression analysis adjustment by age, sex, ApoE ε4, HbA1c, FPG and diabetes duration, history of hypertension, hyperlipemia, CHD, and diabetic complications." (PMID 37700547, 2023). "This was evidenced by the reduction of albuminuria, glomerulosclerosis and mesangial expansion and decreased diabetes‐induced expression of glomerular VEGF, collagen IV and fibronectin in diabetic NOX4−/−ApoE−/− mice versus diabetic NOX4+/+ApoE−/− mice." (PMID 36658776, 2023). "Using human samples and mouse models, we show that ApoE is robustly downregulated in obese individuals, db/db mice, and mice of high-fat diet (HFD) feeding and increased in obese subjects with diabetes." (PMID 38062308, 2023). "Moreover, because we adjusted for parameters including age, sex, education level, diabetes, hypertension, and APOE ε4 status—that is, variables that might affect cognitive function assessment—we conducted more comprehensive statistical analyses compared with prior investigations." (PMID 35616950, 2022). "Apolipoprotein E (APOE) gene mediates lipoprotein clearance and is one of the most studied candidate genes for type 2 diabetes mellitus (T2DM) and coronary artery disease (CAD)." (PMID 35211094, 2022). "Because cardiovascular risk factors (hypertension and diabetes) and WML (eFigure 2, links.lww.com/WNL/B743) have been associated with cognition, these were also adjusted for in another sensitivity analysis along with APOE genotype, to examine whether this would influence the associations." (PMID 35022305, 2022).
diabetes (continued). "Therefore, while high caloric intake and obesity may be a comorbidity factor in the influence of apoE polymorphism on diabetes, whether apoE polymorphism confers diabetes risk in nonobese human subjects is unclear." (PMID 36077289, 2022). "The correlation between HCV eradication and blood levels of ApoB, ApoE, and VLDL should be analyzed in future studies, as these are important subclasses of lipids in the context of diabetes." (PMID 36140194, 2022). "Urinary albumin excretion was reduced in diabetic ApoE KO mice following treatment with an ACE2 minicircle (Mean ± SEM; Diabetes 48 ± 5 μg/day, Diabetes + minicircle 28 ± 3 μg/day, p = 0.008)." (PMID 35624851, 2022). "The opposite directions of effect are observed in relation to APOE-ε2 carriers, who have higher levels of CRP and higher incidence of diabetes, but only a nominal increase in aspirin use." (PMID 34301914, 2021). "The increases in neointimal thickness and lesion burden were significantly reduced in STZ-diabetic ApoE−/− mice treated with acacetin (n = 8, p = 0.0071 vs. STZ-diabetes)." (PMID 33519472, 2020). "Twenty weeks after the induction of diabetes, both C57BL/6 and apoE KO mice diabetic mice exhibited an ~3-fold increase in glycated hemoglobin levels compared to both control and western diet fed mice (p < 0.0001)." (PMID 32581831, 2020). "Previous studies have shown that diabetes is a risk factor for SCM, and hyperlipidemia is a risk factor for diabetes, so it can be speculated that hyperlipidemia is a potential risk factor for SCM, so compared with the normal population, APOE and APOB genes are upregulated in SCM patients." (PMID 32695227, 2020). "The combination of diabetes and hypercholesterolaemia further increased the expression of iNOS and NADPH oxidase, as the levels of these proteins were higher in Ins2+/Akita:apoE−/− mice compared with Ins2+/Akita mice and apoE−/− mice." (PMID 31970899, 2020). "Similarly, western diet feeding had no impact on blood pressure compared to chow fed mice with apoE deletion; however, diabetes was associated with an elevation in systolic blood pressure compared to both chow (p < 0.05) and western diet fed (p < 0.001) apoE KO mice." (PMID 32581831, 2020). "The role of apolipoprotein E gene (APOE) in lipid metabolism has been well established, and APOE is associated with the risk of cardiovascular disease (CVD) and diabetes mellitus (DM)." (PMID 31521122, 2019). "Participants with either a self-reported diagnosis of diabetes (β = 0.160, p = 0.002) or higher HbA1c (β = 0.114, p = 0.014) showed greater WMH progression, but only for APOE e4 carriers." (PMID 28324763, 2017). "In the current study, we found that 8-week treatment with PIO significantly ameliorated the diabetes-induced increases in serum glucose, cholesterol, BUN, and creatinine in apoE (-/-) mice." (PMID 28708885, 2017). "In stage 2 (validation set, n = 619), age, years of education, body mass index (BMI, kg/m2), sex, APOE e4 status, alcohol consumption, smoking status, history of stroke, diabetes mellitus (DM), and hypercholesterolemia significantly differed between the LOAD and control groups." (PMID 27805002, 2016). "Therefore, it was speculated that the APOE gene might also exhibit a certain relevance to diabetes." (PMID 26998902, 2016). "Our data suggest that a HF diet induces diabetes mellitus (DM)-like metabolism in ApoE4 mice, as well as changes in β-site amyloid precursor protein-cleaving enzyme 1 (BACE1) protein levels between the two ApoE strains." (PMID 27656136, 2016). "ApoE gene is one of the most widely studied candidate genes for CAD or any other form of cardiovascular disease and/or diabetes." (PMID 22520940, 2012).